HNF4A (hepatocyte nuclear factor 4 alpha)
Diseases named in the same sentence as HNF4A in open-access papers (continued):
Sharing a sentence is not in itself a finding about the gene and the disease.
colorectal cancer (continued). "HNF4α has also been found to compete with TCF4 and AP-1 at overlapping motifs to regulate distinct genes involved in proliferation and inflammation in colorectal cancer." (PMID 27228072, 2016). "In addition, the positive feedback loop between miR-124 and PKM1/HNF4α plays an important role in colorectal cancer cell apoptosis; it suggests that disrupting this regulatory circuit might be a potential therapeutic tool for colorectal cancer treatment." (PMID 24619225, 2014). "The Cancer Genome Atlas (TCGA) analysis of colon and rectal tumors showed that HNF4α, TOMM34 (outer mitochondrial membrane translocation enzyme 34) and SRC (non-receptor tyrosine kinase) were overexpressed in colorectal cancer." (PMID 36249028, 2022). "Conversely, another study suggested that low HNF4α expression in colorectal cancer reduced the expression of the tumor suppressor gene CDX2 and that the lack of HNF4α function promoted tumor progression." (PMID 30867652, 2019).
colitis (31 papers, 2009 to 2026). Inflammation of the colon. "In IBD patients, HNF4α has low expression, which is consistent with the results in mice lacking HNF4α in IECs, indicating that IECs are more susceptible to drug mediated colitis in mouse models." (PMID 37875976, 2023). "Mice deficient in Claudin 7, hepatocyte nuclear factor 4 alpha (Hnf4a), and Muc2 develop spontaneous colitis." (PMID 35602503, 2022). "Our results reveal similar effects of microbiota colonization and experimental colitis on HNF4A cistrome occupancy in the intestine, but the underlying molecular mechanisms are unresolved." (PMID 28385711, 2017). "Accordingly, loss of function alleles of Hnf4a in mice results in dysregulation of claudin expression and spontaneous colitis." (PMID 28707083, 2017). "Deletion of Hnf4a in murine intestinal epithelial cells results in spontaneous colitis, and HNF4a is a candidate gene at the UC risk locus tagged by rs60173422; however, a role for HNF4a in T cell homeostasis remains unexplored." (PMID 24799394, 2015). "HNF4α is down-regulated in patients with IBD and, moreover, mice with IEC-specific conditional knockout of Hnf4α are more susceptible to chemically induced colitis, indicating that HNF4α is crucial for the barrier function of the intestinal mucosa." (PMID 25593900, 2014). "Additionally, LA can damage the intestinal barrier by binding to HNF-4α, leading to intestinal leakage and further elevating the risk of inflammation and colitis." (PMID 41476793, 2025). "Nobiletin can attenuate dextran sodium sulfate-induced intestinal barrier damage via the HNF4α-Claudin-7 signaling pathway and can cure experimental colitis by reducing inflammation and restoring the damaged intestinal barrier." (PMID 39865231, 2025). "This is consistent with our previous report that DKK2 enhanced Lgr5 expression in colitis-induced cancer cells via HNF4α1, an isoform of HNF4A." (PMID 38659853, 2024). "Previous studies using a DSS-induced colitis mouse model have provided evidence that conditional deletion of Hnf4a leads to a decrease in body mass and an increase in intestinal permeability." (PMID 37635981, 2023). "HNF4α is also expressed in IECs, is reduced in ulcerative colitis patients, and IEC-specific deletion of HNF4α in mice leads to spontaneous colitis that closely mirrors the association of P-gp in protection from colitis." (PMID 35968955, 2022). "In colitis, HNF4α was considered protective against inflammation and genes downregulated in colitis were enriched in HNF4α binding sites." (PMID 29361968, 2018). "HNF4α has two isoforms, P1 and P2, and specific expression of P2-HNF4α in mice promoted RELMβ expression and inflammation in a murine colitis model." (PMID 30297626, 2018). "We also provide genetic and biochemical evidence indicating that RELMβ, a member of the RELM/FIZZ family of cytokines, plays a critical role in the response of HNF4α to colitis and appears to be both directly and indirectly regulated by HNF4α." (PMID 27166517, 2016). "Mouse studies revealed that during intestinal inflammation, HNF4α has a reduced ability to bind to active enhancers and that Hnf4α knock-out mice spontaneously develop colitis." (PMID 27903283, 2016). "Hnf4α, an epithelial specific transcriptional regulator, is decreased in inflammatory bowel disease and protects against chemically-induced colitis in mice." (PMID 19898610, 2009). "Hnf4α is required to protect the epithelium during experimental colitis in young adult mice and is reduced in IBD." (PMID 19898610, 2009). "We confirm that claudin-15 is a direct Hnf4α gene target in the intestinal epithelial context and is down-modulated in mouse experimental colitis and inflammatory bowel disease." (PMID 19898610, 2009). "Animal experiments have shown that the absence of HNF4α increases the susceptibility to colitis and genetic studies have also confirmed its crucial role in maintaining the intestinal barrier function." (PMID 41459538, 2025).
colitis (continued). "HNF4α was reported to be decreased during experimental colitis and IBD." (PMID 19898610, 2009). "Notably, immune regulatory genes were identified as direct transcriptional targets of HNF4α, suggesting that HNF4α restoration could be a strategy to counteract acute colitis with potential relevance for IBD." (PMID 41595461, 2025). "Two HNF4α isoforms P1 and P2 are expressed in different compartments in the colonic epithelium, interact with distinct sets of proteins, and regulate the expression of unique sets of target genes, and thus play distinct roles during pathological conditions such as colitis." (PMID 31139192, 2019). "DSS-induced colitis results in reduced HNF4A protein levels and altered cellular localization; however, our results indicate the microbiota neither reduce HNF4A protein levels nor impact its nuclear localization in jejunal IECs 2 wk after colonization." (PMID 28385711, 2017). "Thus, mice lacking claudin 7, Hnf4a, and Muc2 all develop spontaneous colitis." (PMID 28707083, 2017). "However, no inflammatory defect was reported to occur in animals that were not chemically induced to develop colitis leaving questionable whether Hnf4α was functionally important to maintain appropriate inflammatory homeostasis during adult life." (PMID 19898610, 2009). "This response parallels that seen in mice lacking Hnf4A function in enterocytes, which display intestinal inflammation accompanied by increased sensitivity to DSS-induced colitis and increased permeability of the intestinal epithelium, similar to humans with inflammatory bowel disease." (PMID 27185732, 2016).
inflammatory bowel disease (28 papers, 2009 to 2025). A spectrum of small and large bowel inflammatory diseases of unknown etiology. "In the intestine, dysregulation of HNF4α underlies a multitude of disease phenotypes, notably, inflammatory bowel disease (IBD)." (PMID 37635981, 2023). "Genetic variants at human HNF4A are associated with both Crohn’s disease and ulcerative colitis, and HNF4A is predicted to bind many inflammatory bowel disease–linked cis-regulatory regions and to regulate inflammatory bowel disease–linked genes." (PMID 35533983, 2022). "HNF4A has also been shown to be important in the pathogenesis of inflammatory bowel disease as variants in human HNF4A are associated with increased risk of disease." (PMID 33308304, 2020). "Mutations in the HNF4A gene have additionally or alternatively been associated with renal Fanconi syndrome and inflammatory bowel disease (IBD), attesting to its functions in human renal tubular cells and enterocytes." (PMID 32998360, 2020). "Mutation of Hnf4a in mouse IECs leads to intestinal inflammation and genetic variants at human HNF4A have been linked to inflammatory bowel diseases." (PMID 31555292, 2019). "Interspecies meta-analysis suggested interactions between HNF4A and microbiota promote gene expression patterns associated with human inflammatory bowel diseases." (PMID 28385711, 2017). "Overall, these observations demonstrated that the loss of Hnf4α results in spontaneous chronic inflammation resembling inflammatory bowel disease." (PMID 19898610, 2009). "In the intestine, HNF4α has been implicated in inflammatory bowel disease by GWAS studies." (PMID 34117215, 2021). "HNF4α, a highly conserved transcription factor linked to hemophilia, diabetes, inflammatory bowel disease (IBD) and cancer, is expressed in the liver, intestines, kidney, stomach and pancreas." (PMID 41167395, 2025). "In humans, HNF4α mRNA was decreased in intestinal biopsies from patients with inflammatory bowel disease (IBD) and HNF4α has been linked to IBD in multiple GWAS studies." (PMID 35385524, 2022). "Gene expression analysis reveals that barrier-function-related inflammatory bowel disease (IBD) susceptibility genes (e-cadherin, hnf4a, ttc7a) are suppressed, while inflammatory response genes are stimulated in the mutants." (PMID 29980668, 2018). "In the intestine, genetic deletion of HNF4α leads to loss of mucin-associated genes, increased intestinal permeability, loss of intestinal stem cell renewal (PMID: 31759926) and predisposes to inflammatory bowel disease as well as loss of brush border genes." (PMID 35385524, 2022). "Several IEC signature TFs have known associations with human Inflammatory Bowel Diseases (IBD), including SMAD7, CEBPG, STAT3, XBP1, HNF4A, ELF3, IRF1, and NFκB components IKBKB, IKBKG, and NFKBIZ." (PMID 28850571, 2017). "In humans, HNF4A has been shown to protect the gut against inflammatory bowel disease and there is clear evidence for a role of HNF4A in promoting differentiation of intestinal epithelial cells." (PMID 24533095, 2014). "Additionally, HNF4A maintains intestinal epithelial homeostasis, with dysfunction contributing to inflammatory bowel diseases (IBDs) like Crohn’s disease and ulcerative colitis." (PMID 40926269, 2025). "The anti-inflammatory role of HNF4α is also evidenced by its protective action against inflammatory bowel disease (IBD) and ulcerative colitis." (PMID 34771521, 2021). "HNF4A, a family member of HNF1A, was also identified as an upstream regulator of ACE2 and DPP4 gene expression in patients with inflammatory bowel disease." (PMID 35281029, 2022). "Also, intestinal epithelial cell-specific Hnf4a-null mice were liable to get inflammatory bowel disease (IBD)." (PMID 30582012, 2019).
Insulin resistance (27 papers, 2010 to 2025). Increased resistance towards insulin, that is, diminished effectiveness of insulin in reducing blood glucose levels. "Among them, Pparg and Akt2 (targets of mir-30b), Hnf1b, Hnf4a, and Lmna (targets of mir-30d), are well-known genes implicated in T2D or insulin resistance." (PMID 21124896, 2010). "Interestingly, therefore, for HNF4A, the two signals separate into predominant insulin deficiency and insulin resistance–related mechanisms." (PMID 30240442, 2018). "Reduced HNF4α expression impairs these pathways, resulting in triglyceride accumulation, glucose intolerance, and hepatic insulin resistance, all of which contribute to MASLD progression." (PMID 40926269, 2025). "Inactivation of hepatocyte nuclear factor 4 alpha (HNF-4α) phosphorylation contributes to hepatic insulin resistance." (PMID 38805166, 2024). "Insulin resistance and hyperinsulinemia cause decreased synthesis and production of SHBG by inhibiting hepatocyte nuclear factor 4α (HNF-4α) expression in the liver." (PMID 38044448, 2023). "Gluconeogenesis disorder is the most typical feature of insulin resistance in which HNF-4α synergizes with PGC-1α, FOXO1 and other key enzymes to induce gluconeogenesis, and Leptin regulates the AMPK pathway by inhibiting HNF-4α and promoting SIRT1 expression." (PMID 37705071, 2023). "Our previous study illustrated BBR prevented fructose-induced insulin resistance by promoting the expression HNF4α in rat livers." (PMID 30405404, 2018). "Moreover, PTMs such as SUMOylation and phosphorylation under conditions of oxidative stress diminish HNF4α’s nuclear localization and transcriptional activity, worsening inflammation and insulin resistance." (PMID 40926269, 2025). "The lack of HNF4α impairs β cell functionality, leading to increased susceptibility to glucose intolerance and insulin resistance." (PMID 39741884, 2024). "Hnf4a also increased insulin resistance, DM, glucose tolerance, and inflammatory responses." (PMID 25774879, 2015). "The latest study also proved that berberine could inhibit the fructose-induced insulin resistance in rats possibly through increasing the HNF-4α in liver." (PMID 24250489, 2012). "Dysbiosis—imbalance in the gut microbiome—can disrupt HNF4α-mediated metabolic processes, further contributing to the development of metabolic diseases like MASLD and insulin resistance." (PMID 40926269, 2025). "The genetic variants related to T2DM in Caucasians are mainly related to insulin resistance, but those in Asians, including Chinese, Japanese, and Koreans, are involved in insulin secretion (GLP1R, PAX4, HNF4A, SLC30A8, HHEX, CDKAL1, CDKN2A/B, and GCKR)." (PMID 35956399, 2022). "A study using liver samples from nondiabetic obese patients with NAFLD demonstrated that triglycerides accumulate in the liver and insulin resistance (assessed by homeostatis model assessment, HOMA-IR) was inversely related to SHBG mRNA and to HNF4 α mRNA as well as to circulating SHBG levels." (PMID 33139661, 2020). "An increase in the level of HNF-4α promotes the synthesis of SHBG in the liver, while chronic inflammatory factors may indirectly reduce the level of HNF-4α, which results in a decrease in the production of SHBG and exposure to insulin resistance." (PMID 32992734, 2020). "In contrast to IBD, analysis of intestinal transcriptomic data sets from human subjects with necrotizing enterocolitis (NEC) or insulin-resistance (IR) did not reveal strong enrichment of HNF4A-bound regions near down-regulated genes." (PMID 28385711, 2017). "Adipose tissue insulin resistance increases lipolysis, which in turn releases non-esterified fatty acids (NEFAs) and lipid intermediates which fuel gluconeogenesis and lipogenesis, subsequently inhibiting HNF-4α and reducing SHBG production." (PMID 33139661, 2020).
hyperinsulinism (26 papers, 2010 to 2026). Abnormally high levels of insulin in the blood. "HNF4A is also associated with increased birthweight and a tendency to neonatal hypoglycaemia, which is thought to reflect fetal hyperinsulinemia and the differential roles for HNF4A in fetal and adult beta cells." (PMID 24705260, 2013). "We validated the expression of Hnf4α, a gene that encodes a transcription factor controlling lipid metabolism in the liver, and is downregulated during hyperinsulinemia." (PMID 23342276, 2012). "In addition to hyperglycaemia in childhood/young adulthood, foetuses that inherit an HNF4A mutation from either parent develop hyperinsulinism in utero." (PMID 35445424, 2022). "Knowledge of an HNF4A mutation in either parent therefore has implications for the management of the pregnancy; 50% of foetuses will inherit the mutation and be at risk of macrosomia and hyperinsulinism." (PMID 35445424, 2022). "The p.R76W mutation of HNF4A causes congenital hyperinsulinemia associated with Fanconi syndrome." (PMID 29899848, 2018). "Hyperinsulinemia inhibits HNF-4α expression and reduces the synthesis and production of SHBG in the liver." (PMID 33139661, 2020). "We validated the expression of Hnf4α, a gene downregulated during hyperinsulinemia that also participates in the PPAR pathway, underscoring the importance of IGF-1 to the metabolic effects of CR." (PMID 23342276, 2012). "Previously, we reported that hyperinsulinemia downregulated HNF4α and its target genes through the upregulation of sterol responsive element binding proteins (SREBPs), other important transcriptional factors regulating cholesterol and fatty acid metabolism." (PMID 22190905, 2011). "However, β-cell specific ablation of HNF4α resulted in hyperinsulinemia in utero and reduced blood glucose levels at birth." (PMID 38731997, 2024). "While some HNF4A variants are known to cause congenital hyperinsulinism in the neonatal period, the patient was not overweight at birth nor hypoglycemic, suggesting insulin hypersecretion." (PMID 38745825, 2024). "The fetal insulin hypothesis would predict that affected individuals have a low birthweight, yet individuals with HNF1A-MODY have normal birthweights and inheritance of HNF4A-MODY is associated with fetal and neonatal hyperinsulinism and macrosomia." (PMID 33569631, 2021). "This may explain the molecular mechanism by which hyperinsulinemia downregulates HNF-4α expression, thereby reducing hepatic SHBG production by up-regulating ACC-lipogenesis." (PMID 33139661, 2020). "Interestingly, we also observed an upregulation of Neurod1 and NKx6.1, which are known to increase transcription of the insulin gene and a reduction in HNF4α transcription, known to occur during hyperinsulinemia (excess levels of insulin in the blood)." (PMID 24806840, 2014). "Mutations in eight different genes (ABCC8, KCNJ11, GLUD1, CGK, HADH, SLC16A1, HNF4A and UCP2) have been identified to date in patients with congenital forms of hyperinsulinism (CHI)." (PMID 23032149, 2012). "Among the reported Turkish patients, there was no case with exercise-induced hyperinsulinism (SLC16A1), glucokinase-induced hyperinsulinism, or mutations in the UCP2, HNF4A, and HNF1A genes, while one patient had GLUD1 gene mutation." (PMID 27181376, 2016). "In COPD+NAFLD, the baseline metabolic milieu—characterized by hyperinsulinemia, elevated free fatty acids, and hepatic inflammation—likely sustains high EGR1 expression via MAPK/ERK and NF-κB activation, compounded by disruption of the liver-specific HNF4α/SHP regulatory axis." (PMID 40950963, 2025). "An exception to this notion is that HNF4A mutations cause transient in utero and neonatal hyperinsulinism, which later evolves to decreased insulin secretion, whereas HNF1A mutations develop the latter phenotype without early hyperinsulinism." (PMID 20523905, 2010).